RNU6-223P (RNA, U6 small nuclear 223, pseudogene)
Gene: Small nuclear RNA gene on chromosome 7 (135,960,703 to 135,960,809, forward strand). Ensembl gene ENSG00000199700.
Homologues: Orthologues: chimpanzee U6 (97% identical), macaque U6 (90% identical), dog U6 (82% identical), pig U6 (81% identical), rat U6 (81% identical), mouse Gm25023 (78% identical), dog U6 (74% identical). Paralogues in human: RNU6-19P (86% identical), RNU6-1067P (85% identical), RNU6-12P (85% identical), RNU6-13P (85% identical), RNU6-32P (85% identical), RNU6-41P (85% identical), RNU6-1 (84% identical), RNU6-1060P (84% identical), RNU6-1145P (84% identical), RNU6-116P (84% identical), RNU6-1175P (84% identical), RNU6-147P (84% identical), and 1288 more.